HGF (hepatocyte growth factor)
Diseases named in the same sentence as HGF in open-access papers (continued):
Sharing a sentence is not in itself a finding about the gene and the disease.
liver fibrosis (continued). "Nucleic HDAC7 can bind to the promoter of hepatocyte growth factor (HGF), which leads to the repression of HGF and induces liver fibrosis." (PMID 36864460, 2023). "Another evidence showed that pretreatment of MSCs with basic fibroblast growth factor (bFGF) markedly enhanced the therapeutic effects on liver fibrosis through increasing the secretion of hepatocyte growth factor (HGF) in MSCs." (PMID 37507381, 2023). "In this respect, HGF has important clinical significance to improve liver fibrosis, hepatocyte regeneration after inflammation, and liver regeneration after transplantation." (PMID 36359733, 2022). "Following the promising results obtained in vitro, we investigated the therapeutic potential of ADSCs supplemented with HGF to alleviate or reverse liver fibrosis induced experimentally in diabetic mice." (PMID 36359733, 2022). "In one study of hepatocyte growth factor (HGF) gene delivery as a therapy for liver fibrosis, pCDH-HGF plasmid was loaded onto the cationic liposome surface of microbubble–liposome complexes." (PMID 36365214, 2022). "To evaluate the potential therapeutic ability of ADSCs and HGF to reverse liver fibrosis in a diabetic mouse model, we injected CCl4 i.p. for 7 consecutive weeks." (PMID 36359733, 2022). "HGF derived from MSCs can also accelerate HSCs apoptosis, and MSCs cultured with HGF can improve serum albumin level, reducing liver fibrosis." (PMID 35663940, 2022). "ADSCs supplemented with HGF therapy were able to significantly mitigate CCl4-induced liver fibrosis in diabetic mice by inhibiting the α-SMA and collagen-I expression, results that highlight the key role of HGF in liver recovery after injury." (PMID 36359733, 2022). "In liver fibrosis, nutrients and growth factors related to hepatocytes, such as hepatocyte growth factor (HGF)/epidermal growth factor (EGF) and insulin, can promote proliferation and repair." (PMID 36005144, 2022). "It was observed that hepatocyte growth factor over-expressed MSCs has increased therapeutic effect against experimentally induced hepatic fibrosis compared to normal MSCs." (PMID 36447136, 2022). "Increased expression of miR-16 by HCV infection downregulates hepatocyte growth factor (HGF) and Smad7 in the development of liver fibrosis." (PMID 36016398, 2022). "For example, the proliferation of HSCs and collagen deposition in rats with liver fibrosis were more effectively inhibited by HGF gene-transduced MSC (MSCs/HGF)." (PMID 36685534, 2022). "HGF-modified UCMSCs (HGF-UCMSCs) have been used in the treatment of bronchiolitis obliterans, wound healing, acute kidney injury, and liver fibrosis, among others." (PMID 36726784, 2022). "Coadministration of ADSCs and HGF on diabetic mice with liver fibrosis enhanced antifibrotic effects confirmed by the downregulation of Col I, α-SMA, TGF-β1, and Smad2, while Smad7 was upregulated." (PMID 36359733, 2022). "Human UCMSCs modified with HGF improved liver function and recovered body weight and liver weight, thereby attenuating CCl4-induced liver fibrosis in rats." (PMID 36248254, 2022). "The antifibrotic effect of the ADSCs, HGF, and ADSCs supplemented with HGF was further assessed in vivo on diabetic mice with liver fibrosis experimentally induced." (PMID 36359733, 2022). "HGF has important clinical significance for liver fibrosis, hepatocyte regeneration after inflammation, and liver regeneration after transplantation." (PMID 35370682, 2022). "Our results are in accordance with a previous study which demonstrated that MSCs that overexpress HGF produce improved anti-fibrotic effects on lung and liver fibrosis compared to wild-type MSCs." (PMID 33670243, 2021). "Together, our findings indicated that UDCA provided protection against liver fibrosis through proregeneration via activation of the ID1‐WNT2/HGF signaling pathway." (PMID 33635004, 2021).
liver fibrosis (continued). "Our current study reports a new UDCA mode of action, through which liver fibrosis is alleviated by proregeneration via activation of the ID1‐WNT2/HGF signaling pathway." (PMID 33635004, 2021). "We conclude that UDCA protects against liver fibrosis by proregeneration via activation of the ID1‐WNT2/HGF pathway." (PMID 33635004, 2021). "CXCR7‐ID1‐WNT2/HGF signaling is involved in hepatic regeneration in the PH model, and also plays a positive role in alleviating liver fibrosis." (PMID 33635004, 2021). "Starting from this observation, engineered MSCs overexpressing HGF have been used in a rat model of liver fibrosis." (PMID 33466583, 2021). "In another study, IONP labeling and overexpression of human hepatocyte growth factor (HGF) into MSCs improved the localization of MSCs and supported the liver repair in a rat model of liver fibrosis." (PMID 34578651, 2021). "In this study, we provide evidence that ursodesoxycholic acid (UDCA) can alleviate liver fibrosis by promoting liver regeneration via activation of the ID1‐WNT2/hepatocyte growth factor (HGF) pathway." (PMID 33635004, 2021). "Adoptive transfer of M1 macrophages in a liver fibrosis model promoted recruitment of endogenous “restorative” macrophages that produced HGF and attenuated fibrosis." (PMID 32170906, 2020). "HGF has antifibrotic properties demonstrated in experimental models of lung, kidney, heart, skin, and liver fibrosis." (PMID 33149192, 2020). "It has been demonstrated that the stable expression of HGF in BM-MSCs improved cell homing capacity and differentiation into liver cells, thus alleviating CCl4-induced liver fibrosis in rats." (PMID 33425900, 2020). "Splenectomy prior to MSC administration suppressed liver fibrosis via upregulation of stromal cell-derived factor-1 and HGF, which facilitate the migration of MSCs into injured sites." (PMID 31287024, 2019). "The chains of syndecan-1 are binding several molecules, facilitating intercellular signalling, the most important interactions in liver fibrosis being the ones with TGFβ1, basic fibroblast growth factor (bFGF), and hepatocyte growth factor (HGF)." (PMID 31815014, 2019). "Since one of the major functions of HGF is the induction of matrix metalloproteases (MMPs), such as membrane type 1-MMP and MMP9 to degrade the extracellular matrix, a number of reports demonstrated the therapeutic effect of HGF in liver fibrosis." (PMID 30083132, 2018). "Previous studies reported that administration of recombinant HGF mitigated alcohol-induced liver damage, ischemia-reperfusion liver injury, endotoxin-induced fulminant hepatitis, and liver fibrosis." (PMID 30083132, 2018). "In conclusion, PS-modified NLCs nanoparticles prolonged the retention time of Cur, and enhanced its bioavailability and delivery efficiency to the livers, resulting in reduced liver fibrosis and up-regulating hepatic expression of HGF and MMP-2." (PMID 29214887, 2018). "We observe Lgr5+ liver stem cells in human liver fibrosis tissues, and once they are isolated, these cells are able to form organoids, and treatment with HGF/Rspo1 promotes their expansion." (PMID 29079780, 2017). "As shown by histopathological tests, the DPSC grafting-facilitated reconstruction of the liver architecture and reversal of hepatic fibrosis were further reinforced by HGF overexpression." (PMID 29150644, 2017). "HGF has also been verified to show anti-fibrotic activity in both the onset and progression of liver fibrosis/cirrhosis." (PMID 29150644, 2017). "Though WJ-MSCs secrete higher levels of HGF compared to BM-MSCs, WJ-MSCs showed reduced efficacy in ameliorating liver fibrosis." (PMID 28610623, 2017). "Tβ4 can upregulate the expression of hepatocyte growth factor and downregulate the expression of platelet-derived growth factor-β receptor in a model of liver fibrosis, suggesting an antifibrotic potential of Tβ4." (PMID 27716395, 2016).
liver fibrosis (continued). "A significant decrease of liver fibrosis, accompanied by upregulation of the hepatoprotective and anti-fibrogenic hepatocyte growth factor (HGF), occurred in all IGF-I-treated rats but complete reversal of liver cirrhosis took place only in AAVIGF-I group." (PMID 27658043, 2016). "Rats treated with hepatocyte growth factor (HGF) expressing MSC after small-for-size liver transplantation showed a decrease in hepatic fibrosis compared to rats treated with PBS." (PMID 26981132, 2016). "BCL6B inhibited the activation of HSC though upregulation of HGF, a well-known antifibrogenic mediator, leading to amelioration of hepatocellular damage and liver fibrosis." (PMID 25970780, 2015). "HGF has been used effectively to enhance resolution of experimental liver fibrosis/cirrhosis and regeneration following resection of fibrotic liver." (PMID 25380300, 2014). "This study evaluated the role of ASH1 and EZH2 in two mechanistically different therapeutic modalities, HGF and mMMP-9 gene transfer in CCl4 induced rat liver fibrosis." (PMID 25380300, 2014). "Although the design of our investigation does not allow us to make firm conclusion regarding the partial effectiveness of HGF in enhancing the resolution of liver fibrosis, however, we can propose the following explanations." (PMID 25380300, 2014). "In conclusion, we have demonstrated that mMMP-9 and HGF gene therapy reduce CCl4-induced liver fibrosis in rats." (PMID 25380300, 2014). "HGF-overexpressing ADSCs ameliorated radiation- induced liver fibrosis through down regulation of α-SMA and fibronectin." (PMID 25501583, 2014). "This suggests that mMMP-9 gene transfer is more effective in enhancing resolution of liver fibrosis, at least in early phase of resolution, compared with HGF gene transfer." (PMID 25380300, 2014). "Immunohistochemical staining for fibronectin revealed that radiation-induced liver fibrosis was mitigated by the administration of ADSCs and lenti-HGF + ADSCs." (PMID 25501583, 2014). "Firstly, mMMP-9 is more effective than HGF gene therapy in reducing CCl4-induced liver fibrosis in rats as supported by the documented reduction in all profibrogenic markers." (PMID 25380300, 2014). "Thirdly, ASH1 and EZH2 lysine methyltransferases were markedly induced during progression of liver fibrogenesis but were repressed during the resolution phase of liver fibrosis following mMMP-9 or HGF gene transfer." (PMID 25380300, 2014). "A variety of treatments are being developed to improve fibrosis by interfering with the imbalance in MMPs/TIMPs, such as hepatocyte growth factor in liver fibrosis and all-trans retinoic acid in glomerulosclerosis." (PMID 24396399, 2014). "The present data showed that HGF decreased gradually during the course of DMN-induced liver fibrosis." (PMID 22531084, 2012). "In the present study we investigated the effects of the opposing action of TGF-β and HGF on miR-29 regulated collagen synthesis by HSC during liver fibrosis." (PMID 21931759, 2011). "HGF is considered to be the strongest hepatocyte proliferative agent to date and is able to exhibit a plethora of effects in hepatic fibrosis." (PMID 20509929, 2010). "Notably, UbD deficiency (in UbD−/− mice) suppressed HGF/MET signaling and MDB formation, leading to reduced liver fibrosis." (PMID 42270593, 2026). "In this study, we investigated whether NRP-1 and the HGF/c-Met pathways interact to drive the progression of liver fibrosis." (PMID 40419692, 2025). "Notably, a study using a mouse model of carbon tetrachloride-induced liver fibrosis identified hepatocyte growth factor (HGF) as a key mediator of the antifibrotic properties of SHED-CM." (PMID 40559390, 2025). "Hepatocyte growth factor (HGF)/c-Met signaling critically influences liver fibrosis, but its interaction with neuropilin-1 (NRP-1) in hepatocytes remains unclear." (PMID 40419692, 2025).
liver fibrosis (continued). "Targeting the HGF/RARA/NRP-1 axis may offer a promising therapeutic strategy for managing liver fibrosis, potentially by developing drugs that modulate NRP-1 expression or function." (PMID 40419692, 2025). "This, in turn, reduced ECM deposition and improved liver function, suggesting that HGF may be a promising therapeutic target for liver fibrosis." (PMID 40338014, 2025). "We aimed to investigate whether the NRP-1 and HGF/c-Met pathways interact to drive liver fibrosis progression." (PMID 40419692, 2025). "We evaluated the hepatoprotective activity of rat adipose-derived mesenchymal stem cells (ADMSCs) in combination with platelet-rich plasma (PRP) and recombinant human hepatocyte growth factor (rh-HGF) on a rat model of liver fibrosis/cirrhosis induced by bile duct ligation (BDL)." (PMID 38474368, 2024). "Therefore, the current research was conducted with the objectives of evaluating the hepatoprotective activity of rat ADMSCs in conjunction with PRP and rh-HGF on the liver fibrosis/cirrhosis model, and understanding the impact of their combination." (PMID 38474368, 2024). "Consequently, HGF is considered not only to induce liver regeneration, but also to inhibit disease progression and ameliorate hepatic fibrosis in patients with intractable liver diseases." (PMID 38474368, 2024). "Additionally, pretreatment of human ADMSCs with PRP and recombinant human hepatocyte growth factor (rh-HGF) has been found to enhance the efficacy of stem cell therapy in alleviating liver fibrosis in a mouse model." (PMID 38474368, 2024). "Sami demonstrated that hepatocyte growth factor (HGF)-based ADSC therapy may be useful in the treatment of liver fibrosis in diabetic patients." (PMID 37049846, 2023). "Syndecan-1 chains expedite intercellular signaling by binding numerous molecules; providing for scaffolding of vital connections in liver fibrosis are the ones with transforming growth factor-β1 (TGFβ1), hepatocyte growth factor (HGF), and basic fibroblast growth factor (bFGF)." (PMID 38022112, 2023). "Moreover, in a mouse model of cholestasis-induced liver fibrosis, platelets are activated by HSCs and play an antifibrotic role by reducing collagen I deposition by HSCs through enhancing the HGF-MET signaling pathway." (PMID 38138981, 2023). "Complementarily, we highlighted the inhibitory effects on transdifferentiated hepatic stellate cells, as we observed by electron microscopy analysis of the micrographs from the diabetic mice with liver fibrosis treated with ADSCs and HGF in this experimental group." (PMID 36359733, 2022). "Moreover, stem cell therapy supplemented with HGF considerably attenuated inflammation and microvesicular steatosis, decreased collagen deposits, and alleviated liver fibrosis." (PMID 36359733, 2022). "In addition, HGF-modified ADMSCs alleviated radiation-induced liver fibrosis and promoted liver regeneration as well as liver function." (PMID 36248254, 2022). "In conclusion, the HGF-based ADSC therapy might be of interest for the treatment of liver fibrosis in diabetic patients, consecutive aggression exerts by different environmental factors." (PMID 36359733, 2022). "Moreover, the therapeutic effects of ADSCs were highlighted in vivo on liver fibrosis chemically induced in diabetic mice when supplemented with HGF." (PMID 36359733, 2022). "ADSCs may also ameliorate liver fibrosis by upregulating hepatocyte growth factor (HGF) and downregulating levels of α-smooth muscle actin." (PMID 34805412, 2021). "Also many papers showed with regard to this that different priming approaches, such as 3D cultures of MSCs, IFN-γ and TNF-α treatment, enhance the MSCs production of HGF, making them a potential therapeutic tool to treat liver fibrosis." (PMID 33466583, 2021).
liver fibrosis (continued). "In the result, 3D spheroid MSCs exerted more conducive effects in ameliorating liver fibrosis than 2D cultured cells, possibly via upregulating the expression of antifibrotic factors, such as hepatocyte growth factor (HGF), IL-6, and insulin growth factor 1 (IGF-1)." (PMID 34531915, 2021). "This could be confirmed in murine fibrosis models using carbon tetrachloride (CCl4) or dimethylnitrosurea (DMN), where the injection of platelet-rich plasma (PRP) significantly reduced hepatic fibrosis by increasing fibrolytic markers such as HGF and MMPs." (PMID 33803718, 2021). "Notably, HSCs show a massive upregulation of HGF expression in human liver fibrosis and liver cancer and HGF is stored in the fibrotic and desmoplastic cancer ECM, binding specifically to certain collagens." (PMID 32899119, 2020). "HGFR activation via delivery of recombinant HGF or HGF-expressing plasmids and stem cells decreases lethal liver failure, prevents hepatocyte apoptosis, protects hepatocytes against oxidative injury, and decreases liver fibrosis." (PMID 30979058, 2019). "Additionally, similar results by Lai and co-authors have shown that MSCs that overexpress human hepatocyte growth factor (HGF) promote liver recovery in a rat liver fibrosis model." (PMID 31635053, 2019). "Furthermore, the up-regulated HGF elicits proliferative, survival and anti-inflammatory functions of hepatocytes, indicating that HGF is an important part of mechanism by which Cur-mNLCs reduces liver fibrosis by enhancing hepatocyte protection." (PMID 29214887, 2018). "In the liver, HGF plays a crucial role in liver regeneration after hepatectomy or massive liver damage, protection against hepatocyte apoptosis and necrosis, and suppression of liver fibrosis progression." (PMID 30083132, 2018). "The major producer of HGF in the liver is hepatic stellate cell which is a precursor of myofibroblasts in the liver and contributes to the production of extracellular matrix, progressing to liver fibrosis." (PMID 30083132, 2018). "HGF is well known to suppress hepatocyte death and liver fibrosis." (PMID 29445403, 2017). "For instance, ASCs with overexpression of hepatocytes growth factor (HGF) could ameliorate radiation-induced liver fibrosis through downregulating the expression of α-SMA and fibronectin." (PMID 26649050, 2016). "Additionally, we investigated the role of ASH1 and EZH2 methyltransferases in mMMP-9 and HGF gene therapy-induced resolution of CCl4-model of rat liver fibrosis." (PMID 25380300, 2014). "Hepatocyte growth factor (HGF) gene transfer inhibits liver fibrosis by regulating aberrant cellular functions, while mutant matrix metalloproteinase-9 (mMMP-9) enhances matrix degradation by neutralizing the elevated tissue inhibitor of metalloproteinase-1 (TIMP-1)." (PMID 25380300, 2014). "Given the implications of this research, we hypothesized that ADSCs that overexpress HGF can inhibit apoptosis of hepatocytes, reverse liver fibrosis and promote the regeneration of hepatocytes in a rat model of RILD." (PMID 25501583, 2014). "HGF also inhibits the activation of hepatic stellate cells and collagen deposition in the liver, which reduces the amount of extracellular matrix and improves liver fibrosis by down-regulating the expression of TGF-β1." (PMID 25501583, 2014). "In this regard, haptoglobin has previously been reported as a serum marker of fibrosis in chronic hepatitis C patients, where it is believed that liver fibrosis leads to increased expression of hepatocyte growth factor promoting a subsequent decrease in haptoglobin levels." (PMID 25580050, 2014). "In this respect it has been shown that HGF serum levels correlate with hepatic fibrosis and might serve as a prognostic maker in acute liver failure." (PMID 23516586, 2013). "In addition, HGF is known to inhibit accumulation of extracellular matrix and development of hepatic fibrosis in vivo." (PMID 21931759, 2011).